EGFR (epidermal growth factor receptor)
Diseases named in the same sentence as EGFR in open-access papers (continued):
Sharing a sentence is not in itself a finding about the gene and the disease.
breast carcinoma (continued). "In this study, we found that SUSD2 was a novel target in EGFR+ HER2+ breast cancer." (PMID 39791720, 2024). "Studies suggest that IRESSA may exhibit some effectiveness in certain types of breast cancer, particularly those expressing high levels of EGFR." (PMID 38399423, 2024). "The detectable number of small vesicles with specific protein cargo, including FAK and EGFR, have been found to be increased in patients with breast cancer compared to healthy controls, as have exosomal expression of splice variants of a pro-apoptotic protein called Survivin." (PMID 39518124, 2024). "Additionally, SUSD2 mRNA levels were higher in EGFR+ HER2+ breast cancer than in EGFR+ breast cancer." (PMID 39791720, 2024). "CAR-NK-92 cells based on CD28-CD3ζ signaling domain have anti-tumor cytotoxicity targeting EpCAM and ErB2 breast cancer cells, EGFR on glioblastoma cells and breast cancer brain metastases, CD19 on B-cell malignancies, CS1 on multiple myeloma cells, and CD33 on acute myeloid leukemia cells." (PMID 39633491, 2024). "Additionally, a clinical study (NCT00066378) has revealed that EGFR tyrosine kinase inhibitors (TKIs) can postpone the development of endocrine resistance in breast cancer." (PMID 38751788, 2024). "Previous studies have indicated that the survival of HER2+ breast cancer patients could be influenced by the expression of other oncogenes, including EGFR." (PMID 39791720, 2024). "Additionally, ESR1 demonstrated significant alterations in breast cancer stages, while EGFR showed significant changes in colon cancer stages." (PMID 39204124, 2024). "Through human kinase arrays, we found that STAT3 signaling was activated in EGFR+ HER2+ breast cancer and that the inhibition of STAT3 led to the downregulation of SUSD2 levels, indicating that STAT3 was responsible for upregulated SUSD2 levels in EGFR+ HER2+ breast cancer." (PMID 39791720, 2024). "Furthermore, PTPN3 has been reported to dephosphorylate EGFR, thus increasing sensitivity to tamoxifen and tyrosine kinase inhibitors (TKIs) in breast cancer." (PMID 38173048, 2024). "Advanced analysis of interactions between target proteins obtained from Seagrass E. acoroides Extract and their relationship to breast cancer produced several possible signals in cancer management, such as EGFR tyrosine kinase, pathways in cancer, metabolic pathways, and chemical carcinogenesis-ROS." (PMID 38474594, 2024). "Therefore, SHBG disrupts the loop connecting the two pathways by inhibiting estradiol-induced EGFR expression, thereby reducing the growth of breast cancer cells." (PMID 38465341, 2024). "Additionally, SUSD2 levels were upregulated in SKBR3 and JIMT1 cell lines, which are EGFR+ HER2+ breast cancer cell lines." (PMID 39791720, 2024). "This indicates that the combination of a high migratory signature and EGFR gains may be a prognostic factor for poor outcome in breast cancer patients." (PMID 38892065, 2024). "The ultrasound (US) photoacoustic dual image-guided PTT in a breast cancer mouse model with the newly synthesized anti-EGFR-MPB nanocomposite could be a promising therapeutic approach with enhanced targeted efficiency." (PMID 39525484, 2024). "STAT3 activity was increased in EGFR+ HER2+ breast cancer cells compared to EGFR+ cells." (PMID 39791720, 2024). "This could be ascribed to their interaction with various breast cancer-associated protein targets such as CAs, AKR1B1, ADORA3, PTPN1, ESR2, and EGFR." (PMID 39482666, 2024). "Six compounds, namely GW574783B, GW576924A, GW580496A, GW616030X, GW621823A, and GW633459A, are 4-anilino-quinazolines that bear a strong structural resemblance to lapatinib, used to treat breast cancer by targeting the human epidermal growth factor receptor (EGFR)/(HER) family." (PMID 38590439, 2024). "Ras is aberrantly activated in breast cancers overexpressing EGFR or HER2." (PMID 38601214, 2024). "Consequently, EGFR presents a promising target for the development of effective breast cancer treatments." (PMID 38751788, 2024).
breast carcinoma (continued). "GRh2 liposomes (LTL@Rh2@Lipo-GE11), which target EGFR, were able to counteract breast cancer cells with high EGFR hyperexpression more accurately, showed high specificity and strong cytotoxicity, inhibited the growth and migration of breast cancer cells, and are a promising therapeutic option." (PMID 38957318, 2024). "Meanwhile, in a significant proportion of breast cancers, there is overexpression or amplification of tyrosine kinase receptors such as epidermal growth factor receptor (EGFR) and HER2, leading to increased activation of the phosphoinositide 3-kinases (PI3K) pathway." (PMID 38794316, 2024). "Hence, BEC promote metastatic extravasation through activation of EGFR signalling in breast cancer cells that requires DOCK4, DOCK9, RAC1 and CDC42, rendering them competent for extravasation." (PMID 38762624, 2024). "The epidermal growth factor receptor (EGFR) is a receptor tyrosine kinase that is commonly upregulated in various cancers, such as non-small–cell lung cancer, metastatic colorectal cancer, head and neck cancer, and breast cancer." (PMID 38276624, 2024). "EGFR is known to promote proliferation and survival in breast cancer." (PMID 39698031, 2024). "It has been reported that EGFR could cooperate with integrin αvβ3 to regulate the binding of integrin to extracellular ligands in breast cancer." (PMID 39036079, 2024). "Further, an overexpression of EGFR/ErbB1 and especially ErbB2 is often found in breast cancer." (PMID 38896334, 2024). "However, HER2 (and/or EGFR) heterodimers amplify signaling, providing a potent stimulus for human breast cancer." (PMID 39020378, 2024). "Furthermore, STAT3 inhibitors such as C188-9 and Stattic not only reduced SUSD2 levels, but also suppressed cell growth and cell cycle progression in EGFR+ HER2+ breast cancer cell lines." (PMID 39791720, 2024). "Additionally, in vivo studies using EGFR+ HER2+ breast cancer models will be crucial to explore both the cancer-intrinsic and -extrinsic functions of SUSD2." (PMID 39791720, 2024). "An overnight incubation at 4 °C in a 1:1 DMSO/PBS solution under stirring prompted the loading of Gefitinib, an orally active, epidermal growth factor receptor (EGFR) tyrosine kinase (HR2) inhibitor that is part of breast cancer (SKBR3) therapy within human H-chain ferritin." (PMID 39274893, 2024). "Additionally, estrogen upregulates SIRT1 expression through GPER1, subsequently activating the oncogenic EGFR (epidermal growth factor receptor) signaling pathway, which helps prevent apoptosis in human breast cancer cells, both in vitro and in vivo." (PMID 39684286, 2024). "However, despite the numerous preclinical and clinical trials investigating anti-EGFR inhibitors in breast cancer, only two of them, Lapatinib and Neratinib, have been approved by the Federal Drug Administration (FDA)." (PMID 39405290, 2024). "Similarly, a significant increase in the colocalization of GFP and p‐EGFR (activated EGFR) was observed in the CD24−/CD44+‐breast CSC as compared with the CD24+‐breast cancer cell xenotransplanted groups." (PMID 38522013, 2024). "We next queried the biological processes that may be associated with altered HER3 or other frequently expressed markers in breast cancer, including EGFR, HER2, ER and PR." (PMID 38951909, 2024). "Moreover, TAMs regulate breast cancer stem cell phenotype and promote tumor growth via the EGFR/Stat3/Sox-2 signaling pathway." (PMID 38840908, 2024). "Thus, treating BT474 breast cancer cells with 25 μM genistein for 3 days resulted in reduced expression of EGFR, HER2, and HER3." (PMID 39519572, 2024). "Moreover, the GOBO analysis shows an elevated expression profile of the PTGS2/ESR2/EGFR/JUN/MMP2 genes’ signature in the most aggressive breast cancer subtype (Basal) in breast tumor samples and breast cancer cell lines." (PMID 39707884, 2024).
breast carcinoma (continued). "Another study has assessed the survival rates of 670 breast cancer patients according to EGFR and HER2 expression levels and demonstrated that EGFR+ HER2+ patients have a worse disease-free survival and overall survival than EGFR- HER2-, EGFR+ HER2-, and EGFR- HER2+ patients." (PMID 39791720, 2024). "Several studies showed that the MATH score could be used to evaluate the effect of patient treatment, such as neoadjuvant chemotherapy for breast cancer patients and EGFR TKI for lung adenocarcinoma patients." (PMID 38609450, 2024). "Notably, EGFR is overexpressed in a wide range of breast cancer cells, including in approximately 50% of triple-negative breast cancers (TNBC)." (PMID 38751788, 2024). "Lapatinib, the first TKI approved for breast cancer, targets both EGFR and HER2." (PMID 38243282, 2024). "Albeit biodistribution and efficacy of the nanoplatforms need to be addressed in vivo, our results clearly indicate their high potential as efficient tools for precision phototherapies of breast cancers with overexpression of EGFR and likely other human tumors." (PMID 38532439, 2024). "The comparative study revealed that the spectral shifts obtained for selected breast cancer cells with different degrees of epidermal growth factor receptor (EGFR) expression by PCM were consistent with differences in average EGFR cluster size as determined by dSTORM." (PMID 38116399, 2024). "Interestingly, a study conducted on Lu Lu Tong isolates identified 13 triterpenoids with potential anti-breast cancer effects, via inhibition of multiple protein targets such as ErbB4 and EGFR." (PMID 38371501, 2024). "Another was able to identify a population of EpCAM-negative CTCs isolated from the peripheral blood of breast cancer patients with a unique signature of HER2+/EGFR+/HPSE+/Notch1+ that was then able to generate brain metastases in nude mice as a xenograft, serving as a proof of concept." (PMID 39518124, 2024). "The EGFR signaling pathway plays a significant role in breast cancer development." (PMID 38339275, 2024). "Low levels of miR320 were associated with advanced stage, LNM, and poorer OS in BC patients, as well as serum exosomal miR‐940 levels reflecting the presence of lymph node metastases and EGFR type 2 status, which may be a biomarker for metastasis in breast cancer." (PMID 39015555, 2024). "Considering previous reports and our results, we hypothesized that CCL2 could act as a mediator to determine the aggressiveness of EGFR+ HER2+ breast cancer." (PMID 36674955, 2023). "The CYT1 isoform of HER4 (an epidermal growth factor receptor (EGFR) family member) inhibits cell growth and proliferation in breast cancer, suggesting that it could influence cancer sensitivity to Her-targeting treatment modalities." (PMID 38129384, 2023). "As Axl has been shown to interact with EGFR in breast cancer cells and glioblastoma multiformes, we were interested in whether Gas6 can activate EGFR in both IgR3 and WM852 cells in which both Axl and EGFR are highly upregulated." (PMID 36989239, 2023). "Conversely, a recent preprint found a co-expression of miR-218 and EGFR in breast cancer, hypothesizing that EGFR is indirectly upregulated via miR-218." (PMID 37088795, 2023). "Altogether, these results support a new EGFR–ERα signaling crosstalk mechanism in breast cancer cells, where EGFR signaling dissociates NUTF2 dimers and alters the PTM code to modulate ER signaling and cell growth, along with other critical drivers of cancer growth and metabolism." (PMID 37546719, 2023).
breast carcinoma (continued). "Initial in vitro experiments demonstrated antitumor activity in both HER2-overexpressing breast cancer and EGFR-overexpressing epidermal carcinoma cell lines, with neratinib inhibiting downstream signal transduction events and cell cycle regulatory pathway, and reducing cell proliferation." (PMID 37258523, 2023). "These alterations were detected in 9 NSCLC samples (2 ALK rearrangements and 5 EGFR mutations, 1 BRAF mutation, and 1 G12C/KRAS mutation); 7 breast cancer samples (7 HER2 amplifications); 5 colon cancer samples (5 KRAS mutations); and 3 gastric cancer samples (2 MSI-high and 1 HER2 amplification)." (PMID 36832270, 2023). "The existing data suggest that the epidermal growth factor receptor (EGFR) tyrosine kinase may contribute to breast cancer development and progression." (PMID 36310188, 2023). "Furthermore, in previous reports, inhibition of EGFR enhanced DP expression in breast cancer cells and led to enhanced DP at the cell border in oral squamous cell carcinoma cells." (PMID 36795511, 2023). "Endocytosis of GPR54 and EGFR is modulated by EGF or KP-10 stimulation in breast cancer cells." (PMID 37736108, 2023). "ANXA6 is downregulated in many EGFR (+) and estrogen receptor (ER) (–) breast cancer cells." (PMID 37129645, 2023). "NSCLC, breast cancer and melanoma, which are primary tumor types of LMC may have marker mutations such as EGFR, HER2 and BRAF respectively." (PMID 37096065, 2023). "Clinically, the interaction between PTK6 and EGFR has wide implications, as PTK6 may potentially be a factor in the low efficacy of anti-EGFR drugs in breast cancer treatment." (PMID 37509364, 2023). "In a previous study, the presence of C18:1 promoted MMP-9 secretion through a PKC, Src, and EGFR-dependent pathway suggesting that C18:1 may have a crucial role in the invasion process and metastasis in breast cancer." (PMID 37371132, 2023). "Another study revealed that nuclear translocation of EGFR is regulated by AKT, which is associated with gefitinib resistance in breast cancer cells through enhanced gene expression of the breast cancer-resistant protein (BCRP; also known as ATP-binding cassette subfamily G member 2, ABCG2)." (PMID 37461111, 2023). "Higher EGFR protein levels have been reported in breast cancer, especially in TNBC and IBC." (PMID 37048158, 2023). "Targeting the epidermal growth factor receptor (EGFR) inhibitor in breast cancer with gefitinib was found to reduce the secretion of several proteins that promote tumor angiogenesis and invasion, including vascular endothelial growth factor (VEGF) and interleukin-8 (IL-8)." (PMID 37174117, 2023). "Based on these results, we suggest that pan-HER inhibitors, such as neratinib, could be more effective than TRZ in modulating CCL2 levels in breast cancer with EGFR and HER2 co-expression." (PMID 36674955, 2023). "Furthermore, we identified miR-607, which was constitutively expressed in breast cancer, as a suppressor of EGFR." (PMID 37670360, 2023). "Therefore, we propose that pan-HER inhibitors, such as neratinib and lapatinib, are effective drugs for treating breast cancer with EGFR and HER2 co-expression." (PMID 36674955, 2023). "PELI1 is positively correlated with EGFR expression in breast cancers." (PMID 36841821, 2023). "Taken together, we demonstrated that PELI1 and EGFR cooperated to promote breast cancer metastasis." (PMID 36841821, 2023). "Moreover, ubiquitin carboxy terminal hydrolase-L1 (UCHL1) is involved in regulating the degradation of EGFR and promoting malignant properties in drug-resistant breast cancer, where the specific molecular mechanism needs further research." (PMID 36694209, 2023). "Consistent with these previous reports, our present results show that HER2 overexpression in EGFR+ breast cancer cells could lead to significantly increased cell invasion and cell cycle progression." (PMID 36674955, 2023).
breast carcinoma (continued). "As MET is overexpressed in breast cancer (20%–30%), and METamp and MET overexpressions are associated with anti-EGFR resistance in NSCLC, it was hypothesized that MET contributes to anti-EGFR resistance in TNBC." (PMID 36999986, 2023). "SEMA3C also plays a critical role in the activation of phospho-EGFR levels, a key player in endocrine resistance of ER+ breast cancer cells, suggesting that targeting SEMA3C could be effective in overcoming endocrine resistance." (PMID 37443749, 2023). "In addition, breast cancer cell lines with low levels of EGFR expression were sensitive to GEF when they co-expressed high levels of EGFR2, and this effect is due to the GEF-induced reduction of EGFR1/EGFR2 heterodimerization." (PMID 38090376, 2023). "EGFR localization in invadopodia has also been observed in breast cancer cells." (PMID 38203692, 2023). "However, there is a complexity to the significance of AR expression in breast cancer, with studies showing that the prognostic and predictive power is dependent on the molecular subtype of the tumour, and other factors such as EGFR." (PMID 36831687, 2023). "In addition, our data revealed that ZnPT significantly inhibited multiple aberrantly activated signaling pathways in breast cancer, including EGFR, AKT, and STAT3." (PMID 37953954, 2023). "Similarly, epidermal growth factor receptor (EGFR)-targeted antibody (cetuximab) anchoring PL–DOX (EGFR–PL–DOX) targets EGFR-positive breast cancer cells." (PMID 37375753, 2023). "It has been reported that overexpression of WNT3 activates the Wnt/β-catenin signaling pathway, resulting in transactivation of EGFR and provoking an EMT-like phenotype, which in turn could underlie the trastuzumab resistance of HER2+ breast cancers." (PMID 36831511, 2023). "Furthermore, MET and EGFR are well‐known oncogenes that activate the PI3K/Akt pathway in breast cancer, so trastuzumab cannot completely mitigate this signaling." (PMID 37325934, 2023). "Similarly, albeit through a different mechanism, TXNIP mediates the internalisation and degradation of EGFR, decreasing the migratory capacity of breast cancer cells." (PMID 37794178, 2023). "Likewise, the cell growth regulator with RING finger domain protein 1 (CGRRF1) functioned as a tumor suppressor and identified EGFR as its target in breast cancer." (PMID 36694209, 2023). "In addition, there is heterogenous EGFR genomic instability in various breast cancer groups and ethnicity, and background also contributes to the disparity in the results." (PMID 38090376, 2023). "Currently known oncodrivers in breast cancer are EGFR, HER2, HER3, MET, and mucin-1 (MUC1)." (PMID 36900322, 2023). "Importantly, a few findings have unveiled the involvement of RAB27-regulated EGFR in the progression and lymph node metastasis of epithelial tumors such as breast cancer." (PMID 37685910, 2023). "This might suggest a possibility that Wnt and EGFR crosstalk effects the regulation of HER2+ breast cancer." (PMID 36809986, 2023). "The secretion of IL-8 and IL-1β by TAMs could further enhance the aggressiveness of EGFR+ HER2+ breast cancer." (PMID 36674955, 2023). "The authors demonstrated that these engineered EVs could efficiently target T cells and EGFR-expressing breast cancer cells." (PMID 37842166, 2023). "AREG is a predictive biomarker in the treatment of colorectal cancer and promotes the progression of cancers via the AREG/EGFR pathway in pancreatic cancer, breast cancer and ovarian cancer, suggesting that AREG may be an attractive target in HNSCC." (PMID 37106442, 2023). "This dysregulated activation results from mutations that are frequent in ERα‐positive breast cancers, or the overexpression of growth factor receptors that activate such pathways, such as the EGF receptor (EGFR), which has been linked to endocrine resistance as well." (PMID 36808875, 2023).